CCL19 (C-C motif chemokine ligand 19)
Description:
May play a role not only in inflammatory and immunological responses but also in normal lymphocyte recirculation and homing. May play an important role in trafficking of T-cells in thymus, and T-cell and B-cell migration to secondary lymphoid organs. Binds to chemokine receptor CCR7. Recombinant CCL19 shows potent chemotactic activity for T-cells and B-cells but not for granulocytes and monocytes. Binds to atypical chemokine receptor ACKR4 and mediates the recruitment of beta-arrestin (ARRB1/2) to ACKR4.
Synonyms: ELC; MIP3B; SCYA19; MIP-3b; exodus-3; CKb11
Tractability: Antibody: its Gene Ontology location is reachable by antibodies, with high confidence; UniProt places it where antibodies can reach, with medium confidence; UniProt predicts a signal peptide or a membrane-spanning region.
Gene: Protein-coding gene on chromosome 9 (34,689,570 to 34,691,276, reverse strand). Ensembl gene ENSG00000172724.
Subcellular location: Secreted
Pathways (Reactome):
Signal Transduction: Chemokine receptors bind chemokines; G alpha (i) signalling events
Immune System: Interleukin-10 signaling
Gene Ontology:
Molecular function: CCR chemokine receptor binding; CCR10 chemokine receptor binding; chemokine activity; chemokine receptor binding; protein binding; CCR7 chemokine receptor binding
Biological process: CCL19-activated CCR7 signaling pathway; cellular response to prostaglandin E stimulus; cellular response to virus; dendritic cell chemotaxis; establishment of T cell polarity; myeloid dendritic cell chemotaxis; negative regulation of dendritic cell apoptotic process; positive regulation of canonical NF-kappaB signal transduction; positive regulation of cell motility; positive regulation of ERK1 and ERK2 cascade; positive regulation of JNK cascade; positive regulation of neutrophil chemotaxis; positive regulation of non-canonical NF-kappaB signal transduction; positive regulation of phosphatidylinositol 3-kinase/protein kinase B signal transduction; positive regulation of phospholipase C/protein kinase C signal transduction; release of sequestered calcium ion into cytosol; response to nitric oxide; antimicrobial humoral immune response mediated by antimicrobial peptide; cell communication; cell maturation; chemokine-mediated signaling pathway; eosinophil chemotaxis; immune response; immunological synapse formation; inflammatory response; and 19 more
Cellular component: extracellular region
Genetic constraint (gnomAD): Loss-of-function variants: 6 observed, 12.88 expected, observed/expected ratio (o/e) 0.47, 90% interval 0.25 to 0.92. The upper end of that interval is the gene's LOEUF score, 0.92, which puts it in group 3 of 6, group 1 being the genes least tolerant of losing a copy. Missense variants: 90 observed, 128.55 expected, observed/expected ratio (o/e) 0.7, 90% interval 0.59 to 0.83. Synonymous variants: 40 observed, 50.65 expected, observed/expected ratio (o/e) 0.79, 90% interval 0.61 to 1.03.
Homologues: Orthologues: chimpanzee CCL19 (99% identical), macaque CCL19 (97% identical), dog CCL19 (78% identical), rabbit CCL19 (76% identical), mouse Ccl19 (74% identical), pig CCL19 (72% identical), rat Ccl19 (72% identical), guinea pig CCL19 (66% identical), zebrafish cxcl32b.1 (22% identical). Paralogues in human: CCL21 (36% identical), CCL15 (30% identical), CCL16 (29% identical), CCL18 (29% identical), CCL4 (29% identical), CCL23 (28% identical), CCL24 (28% identical), CCL26 (28% identical), CCL3L3 (28% identical), CCL3 (27% identical), CCL5 (27% identical), CCL17 (26% identical), and 14 more.
Diseases named in the same sentence as CCL19 in open-access papers:
CCL19 is named in the same sentence as 256 diseases in open-access papers, as found by Europe PMC text mining. Sharing a sentence is not in itself a finding about the gene and the disease. The quoted sentences say what the papers report.
breast cancer (34 papers, 2011 to 2025). A primary or metastatic malignant neoplasm involving the breast. "High expression of ACKRs that scavenge CCL19/21 in breast cancer was associated with improved patient survival and reduced rates of metastasis." (PMID 38786066, 2024). "In the plasma of 2208L lung metastasis–bearing mice, we observed an abnormal upregulation of CCL19, which has been associated with breast cancer metastasis, and the expression level decreased with IACS-70654 treatment." (PMID 39287984, 2024). "Multiplex immunofluorescence (mIF) was implemented to identify differential infiltration of Treg, CD8+ T cells, and tumor-associated macrophages, while CCL19 immunohistochemistry was conducted on 182 breast cancer samples from a real-world cohort." (PMID 37944262, 2023). "In the intricate dance of breast cancer, CCL19 has been implicated in a spectrum of activities, ranging from the potentiation of tumor cell growth to the facilitation of invasion and metastasis." (PMID 37944262, 2023). "Despite this, in the TCGA breast cancer patient cohort, CCL19 expression in tumor tissues was associated with increased overall and relapse-free survival (HR for the last tertile vs. first tertile = 0.58, 95% CI = 0.35–0.95)." (PMID 36685922, 2022). "In the subtype-specific analysis, plasma CCL19 was associated with luminal A breast cancer, while CXCL16 was associated with HER-2-enriched breast cancer." (PMID 36685922, 2022). "In the analysis of breast cancer survival, we found a potential causal effect of plasma CCL19 on breast cancer survival (HR = 0.85, 95% CI = 0.75–0.96, p < 0.01), especially for ER-positive breast cancer patients (HR = 0.82, 95% CI = 0.70–0.97)." (PMID 36685922, 2022). "A potential causal association with breast cancer survival was only found for plasma CCL19, especially for ER-positive patients." (PMID 36685922, 2022). "Although not replicated in the UK Biobank, we still found an inverse association between CCL19 expression in tumors and breast cancer overall and relapse-free survival in the TCGA cohort (HR = 0.58, 95% CI = 0.35–0.95)." (PMID 36685922, 2022). "The association between polygenic risk scores for CCL19 and breast cancer mortality in the UK Biobank." (PMID 36685922, 2022). "Notably, up-regulation of CCL19 led to decreased risk scores, aligning with previous findings that higher CCL19 expression is associated with favorable prognosis in breast cancer." (PMID 41288989, 2025). "In addition, we also found an inverse association between CCL19 expression and breast cancer mortality using tumor tissue samples." (PMID 36685922, 2022). "The association between CCL19 and survival of breast cancer patients in TCGA cohort." (PMID 36685922, 2022). "In addition, both genetically predicted plasma CCL19 and CCL19 gene expression in tumors was associated with increased survival of breast cancer in our study." (PMID 36685922, 2022). "In conclusion, we found that lower plasma CCL5 was causally associated with breast cancer, while plasma and tumor-derived CCL19 might be associated with increased survival of breast cancer patients." (PMID 36685922, 2022). "In this respect, overexpression of BCL-XL has been already linked to survival advantage in circulating breast cancer cells that is in line with anoikis-preventing up-regulation of BCL-XL by chemokine (C-C motif) ligand 19 (CCL19) demonstrated in this type of tumor cells." (PMID 26035829, 2015). "CCL19 remains more complex, and as with breast cancer, may be implicated in the spread of melanoma to neighboring lymph nodes through the CCR7-CCL19 axis." (PMID 24762633, 2014). "Finally, CCL19 can be secreted by cells other than cancer cells, while in our study only CCL19 in tumor tissues were used for the validation of its association with breast cancer survival." (PMID 36685922, 2022).
breast cancer (continued). "On the other hand, a study using induced SRC-3 (steroid receptor coactivator-3) Treg cells in a breast cancer model demonstrated that cytotoxic T cells effectively infiltrated into tumors in a CCL19/21-CCR7 dependent manner." (PMID 38786066, 2024). "A study in murine breast cancer C3L5 cells that expressed CCL19 revealed tumor rejection in an NK cell-dependent manner." (PMID 38786066, 2024). "The journey towards a deeper understanding of CCL19 in breast cancer continues, paving the way for innovative approaches to combat this formidable disease." (PMID 37944262, 2023). "Based on the fact that CCR7/CCL19 plays a crucial role in breast cancer development and metastasis, we further explored the IncRNAs and micRNAs associated with it and constructed a ceRNA network." (PMID 37864213, 2023). "Higher expression of CCL19 emerged as a significant predictor of favorable long-term outcomes for breast cancer patients (HR=0.434, p=0.001)." (PMID 37944262, 2023). "Immunohistochemistry (IHC) staining demonstrated elevated CCL19 protein expression in breast cancer tissues." (PMID 37944262, 2023). "Our findings underscore the pivotal role of CCL19 in driving the malignant progression of breast cancer." (PMID 37944262, 2023). "Having explored the prognostic implications of CCL19 expression, our focus shifted to understanding its relationship with immune cell activity in breast cancer (BRCA) and ovarian cancer (OV)." (PMID 37944262, 2023). "Our investigation delved deeper into the influence of CCL19 expression on immune activities, shedding light on its significance in breast cancer (BRCA), ovarian cancer (OV), and across various cancer types." (PMID 37944262, 2023). "It has also been found that CCL19 can increase the heterogeneity of breast cancer cell motility in the 3D microenvironment of breast cancer." (PMID 37864213, 2023). "The CCL19/CCR7 pathway emerges as a pivotal player in breast cancer, notably in the context of lymph node metastasis, and orchestrates a series of intricate molecular mechanisms." (PMID 37944262, 2023). "Through the application of complex machine learning algorithms, we delved into the potential functions of CCL19 in breast cancer (BRCA), ovarian cancer (OV), and pan-cancer contexts." (PMID 37944262, 2023). "Our analysis, encompassing various cancer types sourced from the TCGA database, has unearthed a compelling relationship between CCL19 expression and cancer suppression, particularly evident in breast cancer (BRCA) and ovarian cancer (OV) cases." (PMID 37944262, 2023). "While our study has shed light on the significant role of CCL19 in breast cancer, we acknowledge certain limitations." (PMID 37944262, 2023). "CCL19 in breast cancer is considered an important biological marker for tumor diagnosis and prognosis." (PMID 37864213, 2023). "The study of CCR7/CCL19 chemokine axis and breast cancer (BC) prognosis and metastasis is a current hot topic." (PMID 37864213, 2023). "More importantly, CCL19/CCR7-induced breast cancer cell growth was found to be significantly repressed and anoikis increased when cells were treated with sialyltransferase inhibitors." (PMID 35203305, 2022). "Except CXCL10, high expression levels of CCL5, CCL19 and CXCL9 were significantly associated with better prognosis in breast cancer patients." (PMID 35359417, 2022). "Both findings were more pronounced in ER-positive patients, indicating the potential use of CCL5 and CCL19 as biomarkers or drug targets in future studies for breast cancer prevention and treatment." (PMID 36685922, 2022). "In the present study, we collected the tissues of carcinoma in situ and infiltrating breast carcinoma, and examined the expression of CCL19 through IHC." (PMID 35550569, 2022). "As cooperative ligand binding has been reported in chemokine receptor dimers, we assayed the ability of CXCL12 to potentiate CCL19 interaction with its receptor in the panel of breast cancer cell lines with varied invasive properties." (PMID 34685420, 2021).
breast cancer (continued). "We demonstrate here that the CXCR4 and CCR7 receptor ligands, CXCL12 and CCL19, cooperatively bind and selectively elicit synergistic signalling responses in invasive breast cancer cell lines as well as primary mammary human tumour cells." (PMID 34685420, 2021). "For CCR7, it was reported that sialylation is important for its functions in promoting CCL19 induced breast cancer cell growth." (PMID 32778659, 2020). "A schematic illustration of CCR7 binding to the cognate ligands CCL19/CCL21 to induce several signaling transduction pathways in breast cancer is shown in." (PMID 32340161, 2020). "Findings showed that the EMT progression in breast cancer cells was controlled by the CCL19/CCR7 axis and facilitated the invasion and migration process of tumor cells by triggering several signaling pathways." (PMID 32340161, 2020). "In conclusion, all findings demonstrated that CCL19/CCR7 axis regulated EMT progress in breast cancer cells and mediated the tumor cell invasion and migration process via activation of AKT signal pathway." (PMID 28378417, 2017). "To measure the influence of CCR7 siRNA on CCL19‐induced breast cancer cells proliferation and the cell cycle, we also examined by MTT assay and flow cytometry assay." (PMID 28378417, 2017). "In the present study, we confirmed that CCL19 induces the invasion and migration of breast cancer cells." (PMID 28378417, 2017). "Knockdown of CCR7 inhibits CCL19‐induced breast cancer cell proliferation, the cell cycle, migration, invasion and EMT." (PMID 28378417, 2017). "To measure the influence of AKT pathway in CCL19‐meditated breast cancer cells, we also used Akt1 siRNA." (PMID 28378417, 2017). "Two CCLs were differently regulated; CCL-19 and -24 were unaltered in breast cancers but increased in dense breast tissue." (PMID 29387062, 2017). "In this study, our 3D microfluidic device allows us to observe novel effects of various breast cancer cell lines on the chemotaxis of DCs toward CCL19." (PMID 27451948, 2016). "Our results also indicated that the multilevel microfluidic device offers reliable quantitative data collection, and thus is applicable for the study of the effect of breast cancer-derived soluble factors on CCL19-induced DC chemotaxis." (PMID 27451948, 2016). "In this study, we utilized single cell-based analysis in a 3D microfluidic device and observed that soluble factors secreted from breast cancer cell lines increased CCL19-induced directional persistence of human DCs." (PMID 27451948, 2016). "CCL19, as in breast cancer, slowed tumor growth in a murine colon cancer model while increasing the influx of DC and T cells to the tumor site." (PMID 24762633, 2014). "CCL19 has a more complex role in breast cancer, being used successfully as an adjuvant in cancer vaccines but also is implicated in lymphogenous tumor metastasis." (PMID 24762633, 2014). "CCL19 was the only chemokine found expressed in a significant number of breast cancers and was expressed by both tumor cells and dendritic cells (DC)." (PMID 21624121, 2011). "Our results suggest that CCR6 expression on tumor cells and that infiltration by CCL19-expressing DC contributes to breast cancer dissemination." (PMID 21624121, 2011). "Notably, CXCL5 and CCL19 were 2 chemokines found to be highly expressed in MVI, with CXCL5 having previous associations with metastasis in colorectal cancer and breast cancer." (PMID 39670859, 2025). "Based on these findings, we hypothesize that breast cancer patients with the C2 phenotype exhibit low expression of CCL19, contributing to the creation of an immunosuppressive microenvironment and subsequently leading to poor patient outcomes." (PMID 40340806, 2025). "The realm of breast cancer has been a focal point in the exploration of the CCL19/CCR7 pathway." (PMID 37944262, 2023). "Interestingly, single-cell RNA-seq data revealed expression location of CCL19 in the TME of breast cancer." (PMID 37944262, 2023).
breast cancer (continued). "Specifically, the CCL19/CCR7 signaling pathway assumes a multifunctional role in breast cancer." (PMID 37944262, 2023). "Since we did not replicate the association between CCL19 and breast cancer in the UK biobank, this finding should be interpreted with caution." (PMID 36685922, 2022). "CCL19 significantly enhanced breast cancer patients' prognosis in our work and we speculated it could work in accordance with these immune cells infiltration." (PMID 32195260, 2020). "CCL19 enhanced cell migration and invasion of breast cancer cells." (PMID 28378417, 2017). "However, when administered exogenously both intratumorally or intradermally alongside a Her2/neu DNA plasmid vaccine, CCL19 was able to elicit a Th1 anti-tumor response in a mouse model of Her2/neu positive breast cancer." (PMID 24762633, 2014). "In addition, their respective ligands CXCL12 and CCL19/CCL21 exhibit peak levels of expression in organs representing the first destinations of breast cancer metastasis." (PMID 24915301, 2014). "Pre-treatment of AL10 totally abolished CCL19-induced invasion of breast cancer cells." (PMID 24915301, 2014). "For this reason, CCL19 expression has been associated with the upregulation of adhesion molecules related to migration, the epithelial-to-mesenchymal transition (EMT), and metastasis in breast cancer, cervical cancer, pancreatic ductal adenocarcinoma, and ovarian cancer, among others." (PMID 38786066, 2024). "Based on the analysis of scRNA-seq and bulk RNA-seq data, we built and validated a cancer fibroblast-related risk signature consisting of five genes (BGN, LUM, CCL19, CEBPD, and ID3) that may be utilized as an independent prognostic indicator for breast cancer patients." (PMID 36510567, 2022). "Most importantly, treatment of the invasive mammary tumour cells with the combination of CXCL12 and CCL19 at suboptimal concentrations, elicited a very strong synergistic response in inhibiting cAMP, paralleling results obtained in cells from advanced primary human breast cancer." (PMID 34685420, 2021). "First, we detected whether CCL19 could promote breast cancer cell progression." (PMID 28378417, 2017). "Despite the prevalence of breast cancer (BRCA) and ovarian cancer (OV), there has been a conspicuous gap in our understanding of the prognostic implications of CCL19 in these malignancies." (PMID 37944262, 2023). "This pathway hinges on the binding of CCL19 to its receptor, CCR7, expressed on the surfaces of breast cancer cells." (PMID 37944262, 2023). "Except for CCL19, RAET1G, IL12B, CXCL13, CCL22, and NOS1 were significantly highly expressed in breast cancer at the mRNA level." (PMID 36292723, 2022). "In vitro, endothelin activation of ETA correlated with increased CCR7 cell surface expression in MCF-7, SKBR3 and MDA-MB-231 human breast cancer cell lines, which enhanced MCF-7 invasion of Matrigel towards CCL21 or CCL19 only in the presence of endothelin." (PMID 35203305, 2022). "CCR7 chemokine receptor binds to the ligand CCL19/CCL21 and promotes lymphogenesis and metastasis in breast cancer." (PMID 34544443, 2021). "To begin testing for the functional significance of native CXCR4-CCR7 complexes in breast cancer, we assessed the ability of CXCL12, CCL19 or in combination to inhibit the forskolin-induced increase in cAMP production in MMTV-PyMT primary mammary cells." (PMID 34685420, 2021). "The silencing of CCR7 decreased the in vitro proliferation, migration and invasion of CCL21/CCL19-induced MCF-7 and MDA-MB-231 breast cancer cells." (PMID 32340161, 2020). "For example, the expression of CCL19 and CCL21, ligands of CCR7, was significantly increased in lymph nodes of breast cancer patients." (PMID 32253815, 2020). "Chemokines with well-known functions in mammary cancer include CCL2, CCL5, CCL19, CCL20, CCL21 and CCL22." (PMID 30572845, 2018).